TIMP1 (TIMP metallopeptidase inhibitor 1)
Diseases named in the same sentence as TIMP1 in open-access papers (continued):
Sharing a sentence is not in itself a finding about the gene and the disease.
diabetes (87 papers, 2009 to 2025). "The presence of diabetes mellitus and of preoperative glaucoma were significantly associated with higher TIMP1 levels." (PMID 41009516, 2025). "The balance of MMPs and their inhibitors, TIMPs, is suggested to impact nephropathy, and increased concentrations of TIMP-1 are associated with diabetes." (PMID 39000435, 2024). "Further results of GSEA analysis of TIMP-1 indicated abnormalities in the pentose and glucuronate interconversion signaling pathway, which is strongly associated with diabetes." (PMID 37063869, 2023). "In contrast to these insignificant associations, TIMP1 gene expression as a marker of fat fibrosis was significantly higher in the presence of PN in the diabetes subgroup." (PMID 35651981, 2022). "To conclude, we found that serum 25(OH)D3 concentration was significantly inversely associated with MMP-10 and TIMP-1 levels in patients with diabetes." (PMID 36079742, 2022). "In contrast, a fibrotic gene such as TIMP1 was independently associated with PN (adjusted odds ratio of 1.56; 95% confidence interval 1.06, 2.30) only in subjects with diabetes." (PMID 35651981, 2022). "In our study, statin use was nominally associated with three surrogate marker components (plasma proteins) of GrimAge: ADM, cystatin C, and TIMP-1, all of which are associated with diabetes." (PMID 34083497, 2021). "In contrast, increases of serum and urinary concentrations of TIMP-1 were reported in patients with diabetes, and this increase was associated with greater glomerular lesions." (PMID 32046355, 2020). "Diabetes increased kidney expression of genes associated with injury (Kim1, ten-fold), senescence (Cdkn1a, Cdkn2a, 10 to 18-fold) and fibrosis (Tgfb1, Ctgf, Pai1, Timp1, Col1α1, Col4α1 and Fn1, two- to six-fold)." (PMID 41332229, 2025). "Diabetes mellitus (DM) can cause desmin to become dysregulated, following episodes of nitrosative stress, through the activation of the iNOS/mTOR/TIMP-1 pathway, thereby stimulating collagen deposition in the myocardium." (PMID 35625721, 2022). "If TGF-β1, TGF-β2, TGF-β3, MMP-3, MMP-9, and TIMP-1 are involved in the pathogenesis of DR we hypothesized that their intraocular and eventually also systemic concentrations might be linked to the severity of diabetes and DR." (PMID 34257518, 2021). "In a research investigation involving individuals diagnosed with type 2 diabetes mellitus, a significant correlation was observed between late gadolinium enhancement on cardiac MRI and serum levels of TIMP-1." (PMID 40095713, 2025). "CTGF increased the tissue inhibitor of matrix metalloproteinases 1 (TIMP-1) expression in diabetes, preventing matrix degradation and stimulated EMT in renal tubular cells in diabetes, leading to genesis of new fibroblasts in the renal interstitium." (PMID 38576768, 2024). "For TIMP-1, significant positive associations were found with smoking, CRP and obesity, and an inverse association with prevalent diabetes." (PMID 39917664, 2024). "Significant direct association with TIMP-1 was found for age (p < 0.001), smoking (p = 0.042), CRP (p < 0.001), BMI (p < 0.001), hypertension (p < 0.001), and diabetes (p < 0.001), and inverse association with female gender (p < 0.001)." (PMID 39917664, 2024). "Evidence suggests that skin injuries in diabetes lead to increased production of TIMP-1 and type I and III procollagen in diabetic skin animal models." (PMID 38950058, 2024). "The results indicated that the diabetes group exhibited considerably elevated expression levels of TIMP-1, MMP-2, -3, and -9 genes when contrasted with the control group (p < 0.001)." (PMID 38169923, 2023). "Diabetes, its baseline treatment with metformin, HbA1c, and serum TIMP-1 levels, and LV hypertrophy had moderate positive correlations with LGE-MRI findings (p < 0.05)." (PMID 35628969, 2022).
diabetes (continued). "In contrast, among subjects with diabetes, mRNA expression of TIMP1 and CXCL8 was significantly higher in subjects with PN, and positively correlated with MNSI-PE scores (rho = 0.469, p = 0.001; rho = 0.454, p = 0.002)." (PMID 35651981, 2022). "Diabetes, its baseline treatment with metformin, HbA1c and serum TIMP-1 levels, and left ventricle hypertrophy had moderate positive correlations with LGE findings (p < 0.05)." (PMID 35628969, 2022). "Multivariable analyses adjusted for age, serum CRP level, and diabetes mellitus showed that high serum levels of TIMP-1 were independently related to a diagnosis of motor neuropathy in MPA." (PMID 36362162, 2022). "Comparing healthy diabetics to those with cardiovascular complications revealed a reduction in EG-VEGF and TIMP-4 (in addition to LAP (TGF-b1), Leptin, PD-ECGF, and Serpin F1) in all patients with diabetes with CAD while TIMP-1 was significantly increased." (PMID 35109843, 2022). "In our analysis, including subjects with diabetes, mRNA levels of TIMP1 and CXCL8 were significantly higher in subjects with PN compared with their counterparts." (PMID 35651981, 2022). "In vivo, the ratio of MMP2/TIMP2 and MMP9/TIMP1 was also elevated in the skin of diabetes mice by qPCR analysis Therefore, MMP-2 and MMP-9 inhibitors were administered to the STZ-induced diabetic mice to evaluate the changes in skin collagen in vivo." (PMID 34777244, 2021). "The imbalance of MMP-2/TIMP-2 and MMP-9/TIMP-1 contributes to the skin disorder of collagen deposition in diabetes patients, providing ideas for managing diabetes skin complications early." (PMID 34777244, 2021). "Increased serum levels of MMP-10 and TIMP-1 were found in patients with diabetes compared to healthy subjects." (PMID 31913319, 2020). "TIMP1 is a protein that can promote cell proliferation and is involved in heart failure, diabetes, and cancer." (PMID 31466396, 2019). "Nevertheless, the overexpression of TIMP-1 in pancreatic β-cells pointed protection against diabetes in mice, whereas deletion of this protein provoked an increase in food intake and obesity." (PMID 31581657, 2019). "In relation to TIMPs dysregulation in obese adipose tissue, it has been observed an increase of TIMP-1 and -2 in patients with metabolic syndrome and diabetes." (PMID 31581657, 2019). "The upregulation of certain mRNA isoforms of the ITGA5, TIMP1, ANXA2 and LITAF genes in HIGH pigs is relevant because these four genes have been implicated in human obesity and diabetes." (PMID 29444639, 2018). "Cinaciguat attenuated the diabetes induced proteinuria, glomerulosclerosis and renal collagen-IV expression accompanied by 50% reduction of TIMP-1 expression." (PMID 28894114, 2017). "In our study, diabetes markedly increased TIMP-1 expression and reduced MMP-9/TIMP-1 ratio, leading to reduced MMP-9 gelatinase activity." (PMID 28894114, 2017). "We conclude that the soluble guanylate cyclase activator cinaciguat ameliorated diabetes induced glomerular damage, apoptosis, podocyte injury and TIMP-1 overexpression by suppressing TGF-ß and ERK1/2 signaling." (PMID 28894114, 2017). "Proliferative retinopathy (n = 146) was associated with higher levels of MMP-2 [0.71 (0.45; 0.96)], MMP-3 [0.49 (0.28; 0.70)], MMP-10 [0.39 (0.11; 0.66)] and TIMP-1 [0.54 (0.28; 0.81)] after adjustment for age, sex, duration of diabetes and HbA1c (Model 1)." (PMID 25848912, 2015). "The results of the present study support this data and identified that mandibular advancement increases MMP-8 expression levels and the ratio of MMP-8 to TIMP-1 in condylar cartilage, while diabetes downregulates this augmentation." (PMID 25289023, 2014). "Patients with diabetes had a three times higher ratio of MMP-8/TIMP-1 and twice as high concentration of MMP-8." (PMID 23637817, 2013). "Our findings are also consistent with a previous study that demonstrated decreased TIMP-1 expression in the retina and its microvasculature at both 2 months and 12 months of diabetes." (PMID 23671886, 2013).
diabetes (continued). "Tissue inhibitor of metalloproteinases 1 (TIMP-1) (P01033), ranked the 434th, has been identified as a potential biomarker in diseases such as cancer, cardiovascular diseases and diabetes." (PMID 24324552, 2013). "To investigate if TIMP concentrations differed in the obtained control and diabetes samples we performed Western blotting with antibodies against TIMP-1 and TIMP-2." (PMID 19758433, 2009). "TIMP1 has a role in promoting cell proliferation, and is associated with CVD, diabetes, and cancer." (PMID 34083497, 2021). "We also saw an increase in TIMP-1 levels in the population with diabetes." (PMID 31913319, 2020). "Thus, hyperhomocysteinemia in diabetes activates MMP-9 functionally by reducing Timp1-MMP-9 interactions and transcriptionally by altering DNA methylation-hydroxymethylation of its promoter." (PMID 32150828, 2020). "Also, the triple model (which includes: sofa, diabetes and TIMP1/MMP9 ratio at the first, fourth, and eighth day, does not indicate the AUC of the predictive model, it only shows the AUC of TIMP1/MMP9 ratio, which are not as significant (<70%)." (PMID 28192449, 2017). "The associations between MMP-1, MMP-9, MMP-10, and TIMP-1 with cfPWV did not materially change after adjustment for age instead of age and diabetes duration." (PMID 29070037, 2017). "In a group of 493 patients with and without diabetes complications, we found that high plasma levels of TIMP-1 were associated with CVD." (PMID 25848912, 2015). "Diabetes downregulated MMP-9 expression, the ratio of MMP-9 to TIMP-1 and the total layer thickness of the cartilage, which implies that diabetes may alter the condylar response to mandibular forward positioning." (PMID 25289023, 2014). "Diabetes significantly increased the expression levels of TIMP-1 (P<0.05)." (PMID 25289023, 2014). "TIMP-1 concentrations were elevated in the diabetes group, but this change did not seem to be linked to vascular disease." (PMID 19758433, 2009). "However, we did not observe any association between serum TIMP1 levels and coronary artery disease, diabetes, asthma, or COPD among CRC patients." (PMID 39789100, 2025). "Additionally, circulating levels of TIMP-1 rise in males more than in females, and elevate with well-known CVD risk factors, such as age, body mass index, the ratio of lipoprotein cholesterol, smoking, and diabetes." (PMID 35628490, 2022). "In addition, adjusted OR (95% CI) for PN was 1.56 (1.06, 2.30) for TIMP1 in subjects with diabetes." (PMID 35651981, 2022). "Furthermore the matrix metalloproteinase 1/tissue inhibitor of metalloproteinase 1 (MMP1/TIMP1) pathway may contribute to the breakdown of the blood brain barrier in conditions such as Alzheimer's disease and diabetes." (PMID 23118852, 2012). "Oxidative stress and inflammation in diabetics can increase MAPK activation, leading to reduced activities of COL1 and TIMP1." (PMID 39857349, 2024). "Specifically, in the SBECD + OTX + CHR treatment group, TIMP-1, MMP-2, MMP-3, and MMP-9 expressions dropped approximately by about 29.04, 15.12, 58.77, and 19.41 times, respectively, compared to the diabetes group." (PMID 38169923, 2023). "In univariate analysis, age, CAD, diabetes, CAVI, serum MMP-7, MMP-9, and TIMP-1 correlated with established carotid atherosclerosis." (PMID 37759829, 2023). "First, it was already mentioned earlier that circulating concentrations of TIMP1 (and TIMP2) are significantly increased in patients with metabolic syndrome (MeS), and these levels are even higher in the presence of diabetes." (PMID 37445827, 2023). "In the present study, diabetes upregulated MMP2, TIMP1, and TIMP2 mRNA expression in the human rotator cuff." (PMID 35453426, 2022). "Together with KC, the cytokines TIMP-1, TNFα and IFN-γ, and the chemokines MCP-1 and BCA-1, key players in chronic systemic inflammation occurring in diabetes and obesity, were the most abundant." (PMID 34571976, 2021).
diabetes (continued). "In the late period of diabetes, decreased activity of MMP-2 and MMP-9 is observed with increased activity of tissue inhibitor of metalloproteinases-1 (TIMP-1)." (PMID 32403389, 2020). "MMP-10 and TIMP-1 were significantly higher (p = 0.02 for MMP-10 and p < 0.001 for TIMP-1) in patients with diabetes compared to controls, after adjusting for age, gender and BMI." (PMID 31913319, 2020). "Consistently with the results from isolated cells, the administration of homocysteine to rats significantly exacerbated diabetes-induced increase in MMP-9 activity and its gene transcripts and further decreased Timp1 transcripts and ROS levels." (PMID 32150828, 2020). "Here, our results show that homocysteine supplementation adds to the diabetes-induced increase in ROS generation, increasing MMP-9 activity and decreasing Timp1 levels and also its interactions with MMP-9." (PMID 32150828, 2020). "Investigate effects of long-term exercise on the remodeling markers MMP-9, TIMP-1, EMMPRIN and Galectin-3 in combined type 2 diabetes mellitus (T2DM) and coronary artery disease (CAD) patients." (PMID 31890043, 2019). "Experimental diabetes significantly decreased the ratio of MMP-8 to TIMP-1 and MMP-9 to TIMP-1 compared with that of the NG (P<0.05)." (PMID 25289023, 2014). "In the DG, diabetes decreased the expression levels of MMP-8 and MMP-9 induced by mandibular advancement and increased the expression levels of TIMP-1 compared with that of the NG." (PMID 25289023, 2014). "Intravitreal administration of the ERK1/2 inhibitor U0126 prior to induction of diabetes decreased ERK1/2 activation, attenuated diabetes-induced upregulation of MMP-9, iNOS, IL-6, and TNF-α and upregulated TIMP-1 expression." (PMID 23671886, 2013). "TIMP-1 concentration was higher in groups of individuals with heart conditions, diabetes, and cancer, when compared to individuals without prevalent diseases (p < 0.001)." (PMID 39917664, 2024). "Therefore, this study confirmed that a mixture of Korean red ginseng and probiotics, which are known to be effective in treating diabetes and general wounds, can help heal wounds by controlling the expression of TNF-α, MMP-9, TIMP-1, and NF-κB." (PMID 37374359, 2023). "In the present study, expression of AdamTS4 and Timp1 was up-regulated in regenerating bone fractures of wt and db−/db− generally, whereas up-regulation in bones of mice with diabetes was statistically not significantly higher than in wt bone." (PMID 35207422, 2022). "The imbalance of MMP2/TIMP2 and MMP9/TIMP1 contributes to the non-injured skin disorder of collagen deposition in diabetes, suggesting a possibility for early treatment of diabetes skin complications." (PMID 34777244, 2021). "In diabetes, while retinal MMP-9 expression is upregulated, that of Timp1 is downregulated." (PMID 32150828, 2020). "We did not observe any statistical differences between EV-derived TIMP-1 mRNA and hypertension (p = 0.957) or diabetes mellitus (p = 0.461)." (PMID 32610589, 2020). "The anti-inflammatory TIMP-1 was not altered by diabetes in the lack or presence of HBOT (DM vs. DM HBOT p = 0.0214)." (PMID 31801203, 2019). "Among the top modulated adipokines were inflammatory mediators (C-reactive protein, endocan, EN-RAGE), extracellular matrix regulating factors (Serpin A8, TIMP-1, TIMP-3), and resistin, an adipokine proposed to be an important link between obesity and diabetes." (PMID 30524378, 2018). "Furthermore, they presented three multivariate prediction models of mortality that include TIMP1/MMP9 ratio, diabetes and SOFA score measured at the first, fourth and eighth day." (PMID 28192449, 2017). "The best model for predicting liver inflammation (METAVIR grade 2–3) comprised CXCL10, TIMP1 and APRI (AUROC = 0.798); whereas the best model for predicting steatohepatitis incorporated IL8, ADIPOQ, MMP2, MMP7, age, BMI and diabetes (AUROC = 0.857)." (PMID 27861569, 2016).
diabetes (continued). "Our findings are concordant with clinical/laboratory data that demonstrated a suppression in angiogenesis due to an increase in angiogenic inhibitors in patients with diabetes combined with an increase in CXCL10 and TIMP1 expression at the transcriptional and protein levels." (PMID 26861446, 2016). "Patients with diabetes had higher concentrations of MMP-8 and a higher MMP-8/TIMP-1 ratio." (PMID 23637817, 2013). "MMP-9 expression was significantly higher in diabetic rat retinas compared to controls at all time points.TIMP-1 expression was nonsignificantly upregulated at 1week of diabetes and was significantly downregulated at 4 and 12 weeks of diabetes." (PMID 23671886, 2013). "Interestingly, the mortality rate of SARS-Cov-2 infection combined with diabetes was significantly higher than that of COVID-19 patients without diabetes, further illustrating the key role of TIMP-1 in COVID-19 pathological development." (PMID 37063869, 2023). "Some comorbid conditions other than diabetes mellitus such as renal scars, nephrotic syndrome, focal segmental glomerulosclerosis, pancreatic cancer and chronic kidney failure may also affect urine MMP2 and MMP9, TIMP1 and TIMP2 and TGF-β1 concentrations." (PMID 30396876, 2019). "However our previous studies in fluids from an implant model in diabetic baboons and also in unpublished data from rat wound tissue have shown that TIMP-1 is not altered by diabetes." (PMID 28182694, 2017). "Decreased serum levels of TIMP-1 and TIMP-2 have been observed in patients with T2D and DN compared to diabetes alone or non-diabetes chronic renal failure." (PMID 37237955, 2023). "In some studies, circulating concentrations of TIMP-1 and TIMP-2 are decreased in patients with type 2 diabetes and diabetic nephropathy when compared to non-diabetic CKD or patients with diabetes alone." (PMID 32046355, 2020). "In our study, diabetes treated with oral antidiabetic medication did not influence the plasma levels of MMP-9 and TIMP-1 at any time point." (PMID 30157791, 2018). "In another report, because the ratio of MMP-9 and TIMP-1 is positively correlated with poor healing foot ulcers in patients with diabetes, we surmise that the issue is not high expression of MMP-9 but an inadequate ratio of MMP-9 and TIMP-1." (PMID 25884474, 2015). "A decrease in Timp1 fails to properly interact with increased levels of MMP-9 and aggravates MMP-9 activation, producing a synergistic effect for an already compromised retinal vasculature in diabetes." (PMID 32150828, 2020). "Age, gender, procedure laterality, previous stroke, presence of contralateral stenosis, prior ipsi- or contralateral surgery, smoking, pre-existing hypertension and diabetes treated with oral antidiabetic medication did not influence the plasma levels of MMP-9 and TIMP-1 at any time points." (PMID 30157791, 2018).